TNF (tumor necrosis factor)
Diseases named in the same sentence as TNF in open-access papers (continued):
Sharing a sentence is not in itself a finding about the gene and the disease.
Hyperglycemia (continued). "In the hyperglycemic diabetic model mice used in this study, it has been suggested that hyperglycemia induces pancreatic β cell death and that the inflammatory cytokines such as TNF-α secreted from pancreatic β cells migrate to the brain." (PMID 40559659, 2025). "Hyperglycemia induces a pro-inflammatory phenotype in macrophages, which is characterized by enhanced pro-inflammatory mediator expressions, including IL-1, IL-6, TNF-α, and NO." (PMID 40001441, 2025). "The production of TNF-α by macrophages is induced by chronic hyperglycemia, which exacerbates insulin resistance, promotes atherosclerosis, and contributes to the demyelination of Schwann cells." (PMID 40149566, 2025). "Hyperglycemia causes cellular damage and triggers the release of pro-inflammatory mediators, including the chemokines MCP-1 and TNF-α, which promote macrophage infiltration in the kidney, leading to inflammation and proteinuria." (PMID 40995594, 2025). "Hyperglycemia activates pro-inflammatory cytokines such as IL-6 and TNF-α, which in turn stimulate hepatic CRP production and upregulate MMP-9 expression at the site of tissue injury." (PMID 40364880, 2025). "Hyperglycemia triggers cell damage, leading to the production of various pro-inflammatory mediators, such as interleukin 1 (IL-1) and tumor necrosis factor-α (TNF-α)." (PMID 40995594, 2025). "Conversely, hyperglycemia and pro-inflammatory cytokines, such as TNF-α, IL-1, and IL-6, upregulate iNOS expression, resulting in excessive and sustained NO production." (PMID 41011276, 2025). "Studies have identified an inflammatory response in hypothalamic neurons mediated by IL-1β and TNF-α, which impairs insulin signaling and exacerbates hyperglycemia, further linking metabolic dysregulation with neuroinflammatory processes." (PMID 40218134, 2025). "In the central nervous system, activated microglia release pro-inflammatory cytokines like TNF-α and IL-1β upon exposure to hyperglycemia or oxidative stress." (PMID 40149566, 2025). "Hyperglycemia significantly impaired macrophage phagocytosis and bactericidal activity while inducing pro-inflammatory mediator markers, IL-1, IL-6, TNF-α, and iNOS." (PMID 40001441, 2025). "Previous reports have predominantly used TNF-α or VEGF, whereas we have mimicked the diabetic milieu using three of the primary drivers of DRD development in humans simultaneously: hyperglycaemia, inflammation (TNF-α and IL-1β) and VEGF." (PMID 40664761, 2025). "Studies have shown that hyperglycemia activated the production of inflammatory cytokines such as TNF, IL6, and IL1B, which contribute to kidney damage." (PMID 39911324, 2025). "A study demonstrated that hyperglycemia induces excess ROS production from mononuclear cells, which subsequently triggers the release of tumor necrosis factor-α (TNF-α)." (PMID 39850484, 2024). "Meanwhile, hyperglycemia and tumor necrosis factor-α (TNF-α) decrease androgen receptors through nuclear factor kappa B (NF-kB), thereby reducing the risk of prostate cancer." (PMID 39076779, 2024). "Our results demonstrate that hyperglycemia affects TCR-specific stimulation which hampers CD8+ T cell function by reducing the expression of TNF-α." (PMID 38214784, 2024). "Usually, we can find an overexpression of TNFα (tumor necrosis factor α), interleukin-1, and interleukin-6 in chronic wounds, originating from hyperglycemia and persistent wound inflammation." (PMID 38392639, 2024). "In the presence of hyperglycemia, the proinflammatory cytokines (TNF-α, growth factors, IL-1, IL-6) increase and are believed to be involved in the initiation and exacerbation of inflammation in DR." (PMID 38540165, 2024). "TNF-α promotes carbohydrate dysregulation (hyperglycemia) by inhibiting insulin action, reducing glucose clearance (primarily by muscle and adipose tissue), and increasing hepatic glucose production." (PMID 39204094, 2024).
Hyperglycemia (continued). "Inflammatory factors, such as IL-6, TNF-α, cleaved caspase-1, and pro-IL-1β are downstream of the NF-κB signaling pathway and are also involved in neuroinflammation induced by hyperglycemia." (PMID 38421831, 2024). "Hyperglycaemia is characterised by elevated levels of serum acute phase proteins and many cytokines (such as TNFα, lL-6, lL-1β) and can trigger monocytes to produce pro-inflammatory cytokines and chemokines." (PMID 38962295, 2024). "Persistent hyperglycemia activates nuclear factor kappa-light-chain-enhancer of activated B cells (NF-κB), inducing the production of pro-inflammatory cytokines such as tumor necrosis factor-alpha (TNF-α) and interleukin-6 (IL-6)." (PMID 39872596, 2024). "During inflammatory responses, hyperglycemia and oxidative stress induce PTECs to release large amounts of pro-inflammatory factors such as TNF-α and IL-6." (PMID 39795078, 2024). "For instance, hyperglycemia leads to the production of a wide range of pro-inflammatory factors, such as interleukin-6 (IL-6), tumor necrosis factor-α (TNF-α), and cyclooxygenase-2 (COX-2), all closely connected with pro-tumorigenic actions." (PMID 38892104, 2024). "Increased levels of ROS produced by mononuclear cells during physiological hyperglycemia trigger the release of tumor necrosis factor (TNF) and increase the levels of a pro-inflammatory transcription factor, nuclear factor-kappa B (NF-κB)." (PMID 36835217, 2023). "Hyperglycemia triggers microglial responses through enhanced autocrine TNF-α signaling, which activates NF-κB and its downstream inflammatory genes." (PMID 36869375, 2023). "The endogenous production of TNF-α increases at the level of microvascular and neuronal tissues in the case of chronic hyperglycemia." (PMID 37629665, 2023). "The decreased secretion of anti-inflammatory adiponectin and the increased secretion of pro-inflammatory leptin and IL-6 is reported in GDM, similar to high concentrations of TNF-α and IL-1β due to hyperglycaemia." (PMID 37627482, 2023). "In all participants, hyperglycemia led to significant reductions of 62/70 inflammatory markers across all subcategories including TNF-α, IL-8, IL-18 and VEGF-A." (PMID 37400734, 2023). "The placental tissue of women with GDM induces pro-inflammatory gene expression (tumor necrosis factor-α, TNF-α) that dysregulates insulin signaling and reduces insulin secretion from β-cells under the condition of hyperglycemia." (PMID 37239377, 2023). "Hyperglycemia is involved in molecular inflammatory mechanisms inducing TNF-α release and promoting apoptosis of hippocampal neurons." (PMID 36768341, 2023). "In this study, intermediate hyperglycaemia caused a significant increase in CRP, TNF-α and IL-6 concentration in the PD compared to the NPD group." (PMID 38024366, 2023). "In response to hyperglycemia, mononuclear cells produce tumor necrosis factor-α (TNF-α), which can exacerbate the metabolic abnormalities of PCOS20." (PMID 37355686, 2023). "It is well accepted that hyperglycemia leads to the expression of higher serum levels of pro-inflammatory cytokines such as interleukin-6 (IL-6), IL-8, IL-1β, and tumor necrosis factor-a (TNF-α) in women with GDM compared to normal pregnancies." (PMID 37190095, 2023). "The increase in the inflammatory cytokine TNF-α induced by hyperglycemia and insulin resistance can trigger cell damage and eventually lead to myocardial fibrosis in DCM patients." (PMID 37479697, 2023). "In vitro studies have demonstrated the dapagliflozin-mediated attenuation of TNF-α- and hyperglycemia-induced increases in ICAM-1, VCAM-1, PAI-1 and nuclear factor-kappa B (NFκB) expression." (PMID 37367894, 2023). "ML204 exacerbated hyperglycaemia, dyslipidaemia, fat tissue deposition, hepatic steatosis, and adipose tissue and liver TNFα in HS-fed mice." (PMID 37631015, 2023).
Hyperglycemia (continued). "Results revealed hyperglycemia, hypoinsulinemia, increased MDA, TNF-α, IL-6, and NF-κB levels, in association with reduced CAT, SOD, GSH, Nrf2, and HO-1 levels in LCT group." (PMID 37463968, 2023). "In hyperglycemia condition, the excessive production of ROS lead to the release of pro-inflammatory cytokines such as IL-6, IL-1β, TNF alpha, and INFy." (PMID 37175192, 2023). "Laboratory research on the impact of hyperglycemia on TNF-α production in cancer cell biology is limited." (PMID 36765695, 2023). "There is evidence that hyperglycemia increases the secretion of tumor necrosis factor alpha (TNF⁃α), interferon γ (IFN⁃γ), resistin, and interleukin-6 (IL-6), leading to tumor-related inflammation." (PMID 36672448, 2023). "TNF-α and hyperglycemia have been reported to elevate plasminogen activator inhibitor-1 (PAI-1) and ICAM-1 and VCAM-1 expression in endothelial cells." (PMID 37367894, 2023). "It was found that PCP was effective in suppressing hyperglycemia, hyperinsulinemia, and the expression of inflammatory cytokines (IL-6 and TNF-α), and boosting glucose tolerance in db/db mice." (PMID 37689643, 2023). "After confirming hyperglycemia, the mice received an intravitreal injection of either proinflammatory cytokines (TNF-α and IL-1β) or vehicle." (PMID 36895267, 2023). "In patients with hyperglycemia, researchers have detected chronic low-grade, subclinical inflammation mediated by TNF-α, COX-2, IL-1β, IL-6, and MCP-1, which is responsible for vascular complications." (PMID 36982499, 2023). "Hyperglycemia promotes the production of proinflammatory cytokines TNF-α and IL-6 production, and the expression of these proinflammatory cytokines induces an increase in MMP9 expression in an autocrine and paracrine manner." (PMID 36820318, 2023). "In cultured macrophages, intermittent episodes of hypoglycemia and hyperglycemia promote M1 polarization and enhance IL-1β, TNF-α, IL-6, and MCP-1 secretion." (PMID 37893217, 2023). "Hyperglycemia is probably a sign of an active inflammatory response that is accompanied by an increase in tumor necrosis factor (TNF) activated by nuclear factor kappa b (NF‐β)." (PMID 37324871, 2023). "The byproducts of hyperglycaemia, AGEs, regulate inflammation by increasing NF-κB nuclear localisation and induction of IL-1β, TNF-α, macrophage inflammatory protein 2 (MIP2), IL-6 and IL-10." (PMID 37670018, 2023). "An experimental model has demonstrated that hyperglycemia can increase levels of inflammatory cytokines, including interleukin-6 and tumor necrosis factor-alpha, which play a crucial role in epithelial-to-mesenchymal transition and tumorigenesis." (PMID 37181380, 2023). "Specifically, in DM, hyperglycemia induces elevation of inflammatory factors, such as tumor necrosis factor α (TNF-α) and E-selectin in the CNS, and this is accompanied by blood–brain barrier (BBB) disruption and memory impairment." (PMID 36768341, 2023). "It has been demonstrated that spermatogenesis and steroidogenesis are inhibited by hyperglycemia-induced OS and increased levels of pro-inflammatory markers, IL-1 and TNF-α." (PMID 37895159, 2023). "Accumulating evidence has demonstrated that hypoxia, reactive oxygen, nitrogen species, hyperglycemia, cytokines TNFα, and INFγ induce tumor cells to actively secrete HMGB1 into the extracellular matrix." (PMID 38003396, 2023). "Similar results have proved that insulin group and hyperglycemia have more enhanced systemic inflammation and higher inflammatory markers including D-dimer, C-reactive protein, TNF-a and other interleukins." (PMID 35725489, 2022). "Upregulation of Nqo1 in cultured vascular cells by adenovirus vectors also decreased the expression of hyperglycemia-mediated endothelial adhesion molecule and tumor necrosis factor -α and prevented smooth muscle cell migration." (PMID 35739970, 2022).
Hyperglycemia (continued). "Decreased insulin sensitivity and increased glucose production lead to decreased islet cell function and hyperglycemia, as well as increased release of inflammatory factors (such as IL-6, TNF-α, and C-reactive protein)." (PMID 35432188, 2022). "The release of the acute-phase inflammatory cytokine TNFα was stimulated by Hb-Hp1-1 complexes after 6 h in NG, with this effect being significantly enhanced by hyperglycemia." (PMID 35163309, 2022). "But what is certain is the worsening of hyperglycemia and increased incidence of diabetic ketoacidosis that can be attributed to enhanced production of IL-6 and TNF-α in response to SARS-CoV-2 infection." (PMID 36778598, 2022). "PBA notably diminished hyperglycemia-enhanced expression of TNF-α and IL-6, and elevated hyperglycemia-reduced expression of IL-10 at 0 and 6 h after reperfusion." (PMID 35289326, 2022). "Under hyperglycemia, the production of IL-1β, IL-6, and TNF-α is promoted, thereby accelerating the apoptosis of islet β cells and inducing islet failure." (PMID 35845591, 2022). "Consumption of calorie dense diet and high fat diet (HFD) produces elevation in the production of IL-6 and TNF-α that, in turn, aggravates hyperglycemia." (PMID 36778598, 2022). "Hyperglycemia also leads to persistent inflammation, expressed by elevated levels of pro-inflammatory cytokines and inflammatory markers, e.g., tumor necrosis factor α (TNF-α) and C-reactive protein (CRP)." (PMID 36555387, 2022). "TNFα can even increase the process of glycogenolysis and impair glucose uptake, which in turn increases the blood glucose level leading to hyperglycemia and increased AGE levels." (PMID 35625570, 2022). "The persistent hyperglycaemia can alter the release and functionality of inflammatory cytokines like interleukin 1 (IL-1), interleukin 6 (IL-6) and tumour necrosis factor-a (TNF-a), leading to an increase in T2DM." (PMID 36419622, 2022). "In the current work, mTOR contributes to DPN development in STZ receiving animals due to hyperglycemia-reduced AMPK activation or -enhanced TNF-α, which were formerly documented." (PMID 35767208, 2022). "Poor periodontal status in proportion to poor glycemic control is a result of hyperglycemia-induced accelerated expression of inflammatory mediators such as Interleuikin-6 (IL-6), Tumor necrosis factor-Alpha (TNF-α), and toll-like receptors." (PMID 36557041, 2022). "The free oxygen radicals and advanced glycation products induced by hyperglycemia were reported to enhance the production of inflammatory cytokines including TNF-α." (PMID 35164292, 2022). "In an in vivo study, BAY 11–7082 (a selective NF-κB inhibitor) protects rats from diabetic nephropathy through decreasing the expression of inflammatory factors such as TNF-α and IL-6 and suppressing the oxidative damage regulated by hyperglycaemia." (PMID 35251212, 2022). "TAU prevents apoptosis induced by hyperglycemia, lipopolysaccharide, and tumor necrosis factor-alpha stimulation and reduces oxidative stress in HUVECs and other human endothelial cells not stratified for sex." (PMID 36670939, 2022). "The consistent hyperglycemia leads to the accumulation of advanced glycation end products and induces nuclear factor-κB( NF-κB), transcription factors related to cytokines like TNF-α." (PMID 35836916, 2022). "Periodontal disease has been associated to the generation of proinflammatory mediators connected to hyperglycemia (IL-6, TNF-α, and CRP)." (PMID 36557312, 2022). "Hyperglycemia is also correlated with increased inflammatory markers, including tumor necrosis factor-α (TNF-α), interleukin (IL)-6 and C-reactive protein (CRP)." (PMID 35330131, 2022). "Hyperglycaemia has been shown to increase TNF-α, NF-κB activity and VEGF production in ARPE19 cells." (PMID 38983565, 2022).
Hyperglycemia (continued). "Nevertheless, proinflammatory cytokine IL-18 was reported to be elevated in newly diagnosed T2DM and prediabetic patients, and acute hyperglycemia was shown to induce the increase in plasma IL-6, TNF-α, and IL-18 concentrations." (PMID 36547931, 2022). "The HCHF diet was found to promote hypertension, hyperglycemia, and hypertriglyceridemia, and to increase brain TNF-α levels." (PMID 36358526, 2022). "In conclusion, this study showed that 12 weeks of Eriomin supplementation, at 200 mg/d, resulted in a reduction in hyperglycemia (−5%), and a diminished inflammatory response, by decreasing blood serum markers IL-6 (−14%) and TNF-α (−20%)." (PMID 35796695, 2022). "TNF-α also has an effect on glucose metabolism, and the placenta also shows higher secretion of TNF-α under the condition of hyperglycemia." (PMID 36615730, 2022). "Animal experiments showed that GGQL can effectively reduce the levels of insulin, HOMA-IR, TNF-α, and IL-17 and improve the state of hyperglycemia." (PMID 36284987, 2022). "The values plotted are the mean RFU values (log2 scaled for 3 replicates) for TNFα-stimulated HUVECs in hyperglycemia (y-axis) versus hyperglycemia (x-axis) alone groups." (PMID 34045516, 2021). "All 17 KRIS proteins were present in both intracellular and extracellular HUVECs fractions following TNFα treatment in hyperglycemia condition." (PMID 34045516, 2021). "Alternatively, hyperglycemia contributed to Kupffer cells activating and then secreting proinflammatory cytokines such as TNF-α and IL-6." (PMID 33809508, 2021). "In keratinocytes, hyperglycemia dose-dependently up-regulates the expression of TNF-α to reduce the expression of Thrombomodulin (TM) and TLR4, exogenous supplementation of Recombinant sTM can increase the expression of TLR4 and promote DW healing." (PMID 33967796, 2021). "Since hyperglycemia activates NF-κB and cytokines such as TNF-α, which besides activating NF-κB is known to stimulate AR gene expression, it is necessary to further understand the relationship and molecular mechanism underlying these signals." (PMID 34677370, 2021). "Hyperglycemia-induced production of interleukin-1β (IL-β), interleukin-6 (IL-6), tumor necrosis factor-α (TNF-α), and chemokine ligand-2 (CCL2) by Müller cells is linked to retinal cell death." (PMID 33875782, 2021). "Hyperglycemia activates the production of multiple proinflammatory cytokines (e.g., IL-1, IL-6, and TNFα) and leads to the recruitment of inflammatory cells to the kidney." (PMID 34200774, 2021). "It was reported that the free oxygen radicals and advanced glycation products (AGEs) prompted by hyperglycemia can enhance the production of inflammatory cytokines including TNF-α." (PMID 34568337, 2021). "These significant proteins are marked on the scatterplots, and unmarked dot points indicate proteins that were unaffected by exposure to hyperglycemia and TNF-α treatment." (PMID 34045516, 2021). "Specifically speaking, under the condition of hyperglycaemia, the elevated pro‐inflammatory cytokine, such as TNF‐α and macrophage migration inhibitory factor (MIF), regulates glucose metabolism during systemic inflammation." (PMID 34213839, 2021). "Postprandial hyperglycemia observed after carbohydrate intake induces pro-inflammatory cytokine expression, including interleukin 1 beta (Il1b) and tumor necrosis factor-α (Tnfa) in peripheral leukocytes." (PMID 34336926, 2021). "In DKD, hyperglycemia-mediated PKCβ and PKCδ activation in the renal cortex leads to activation of NF-κB and release of TNF-α by endothelial and mesangial cells." (PMID 34202668, 2021). "Reduction of the kidney SOD enzymes was demonstrated in KK/Ta-Akita mice after 5-week hyperglycemia mediated by TNF-α and interleukin-1β (IL-1β)." (PMID 34326888, 2021). "TNF-α exhibited a complicated intersection with T1DM and caused the beta-cell injury that was followed by chronic hyperglycemia." (PMID 34572503, 2021).